TIMP2 (TIMP metallopeptidase inhibitor 2)
Diseases named in the same sentence as TIMP2 in open-access papers (continued):
Sharing a sentence is not in itself a finding about the gene and the disease.
myopia (continued). "During the development of visual deprivation myopia, the expression level of MMP-2 in the scleral fiber layer of chickens was elevated compared with that of normal controls, while the expression level of TIMP-2 was decreased compared with that of normal controls." (PMID 40375931, 2025). "Consequently, elevated MMP-2 in myopia results from: Disrupted dopamine signaling (light exposure to D2R activation and MMP-2); Therapeutic MMP-2 inhibition (e.g., TIMP-2 gene therapy, doxycycline) synergizes with cAMP-elevating agents to preserve scleral integrity." (PMID 40933557, 2025). "MMP-2 and TIMP-2 could affect scleral ECM and mediate the scleral remodeling during myopia." (PMID 35783515, 2022). "Interestingly, a recent study have shown that low doses of TIMP-2 promote MMP-2 activation, whereas high doses inhibit its activation, reduce collagen degradation, and shorten the AL, suggesting that TIMP-2 supplementation may be helpful in controlling myopia progression." (PMID 39430251, 2024). "The significant correlations of choroidal thickness with MMP-2 and TIMP-2, but not with VEGF-A further suggests that the mechanisms resulting in thinning of choroid observed in high myopia may be related to mechanical factors rather than ischemic factors." (PMID 31673022, 2019).
atherosclerosis (16 papers, 2014 to 2025). A disease characterized by the build-up of fatty material and calcium deposition in the arterial wall resulting in partial or complete occlusion of the arterial lumen. "Levels of proteins (osteoprotegerin, osteopontin, osteocalcin, matrix γ-carboxyglutamic acid protein, fetuin A, MMP-2, MMP-9, TIMP-1, TIMP-2) and biochemical parameters were measured to analyse their influence on atherosclerosis risk in CKD patients." (PMID 26843213, 2016). "In a mouse model of atherosclerosis using overexpression of Timp-1 or Timp-2, a study in a model of early atherosclerosis revealed a reduction of atherosclerotic plaques rather for Timp-2 than Timp-129." (PMID 37675562, 2023). "In particular, resveratrol increases TIMP-2 and decreases MMP-2 and thereby regulates the MMP-2/TIMP-2 ratio, leading to an improvement of atherosclerosis-induced myocardial fibrosis." (PMID 36615832, 2022). "Knockout of TIMP-1 and gene transfer of TIMP-1 and TIMP-2 in mice can accelerate the atherosclerosis formation and make atherosclerotic plaque unstable." (PMID 29435135, 2018). "MMP-2 and TIMP-2 expression can be regulated by fluid shear stress, which are important factors contribute to atherosclerosis." (PMID 29435135, 2018). "Our data demonstrate that TIMP-2 plays a greater protective role than TIMP-1 during the pathogenesis of atherosclerosis, in part by suppressing MMP-14-dependent monocyte/macrophage accumulation into plaques." (PMID 26645981, 2016). "Furthermore, miR-483-5p targeting TIMP metallopeptidase inhibitor 2 (TIMP2) promotes atherosclerosis development and endothelial dysfunction by inhibiting autophagy." (PMID 40823532, 2025). "As overexpression of TIMPs is postulated to attenuate atherosclerotic plaque development and instability, it was an unexpected finding that TIMP-1 levels were lower with exercise in both the early- and late-stage model of atherosclerosis; however, TIMP-2 levels were unchanged." (PMID 35419434, 2022). "It is also possible that the beneficial effects TIMP-2 exert on atherosclerosis may be through the suppression of numerous proteolytic substrates and the modulation of other resident cell types within atherosclerotic lesions." (PMID 26645981, 2016). "Although TIMP-2 overexpression did not impart any protective effects in atherosclerosis or cardiac fibrosis, longer-term studies would be appropriate to evaluate its therapeutic potential to combat the progression of both diseases." (PMID 34848763, 2021). "In this study, significantly increased levels of MMP-2, MMP-2/TIMP-2 ratio and lower levels of TIMP-1 were observed, suggesting that these factors may be involved in the pathogenesis of atherosclerosis in patients with CKD." (PMID 26843213, 2016). "Significantly increased levels of MMP-2, MMP-2/TIMP-2 ratio and lower TIMP-1 suggests that these factors may be involved in the pathogenesis of atherosclerosis in CKD patients." (PMID 26843213, 2016). "Indeed, our findings support that atherosclerosis development is accompanied by an increase in MMP-2, MMP-3, MMP-8, MMP-9, TIMP-1 and TIMP-2 levels." (PMID 25264981, 2014). "SNPs can also interfere with the balance of MMPs and TIMP-2 in the absence of acute BBB disruption, thereby influencing the development and severity of atherosclerosis, white matter lesions, and small-vessel disease." (PMID 25280484, 2014). "We present novel data showing that TIMP-2 but not TIMP-1 acts as an important modulator of the MMP-14-directed monocyte/macrophage invasion that reduces accumulation in atherosclerotic lesions in vivo and therefore plays a protective role during the pathogenesis of atherosclerosis." (PMID 26645981, 2016).
COVID-19 (16 papers, 2020 to 2025). A disease caused by infection with severe acute respiratory syndrome coronavirus 2. "For instance, urine [TIMP-2]x[IGFBP7] results have been shown to predict moderate to severe AKI in patients with severe COVID-19 and acute respiratory distress syndrome." (PMID 40055234, 2025). "In critically ill patients with COVID-19, the combination of [TIMP-2] × [IGFBP-7] and clinical data proved helpful in identifying subclinical AKI." (PMID 39001241, 2024). "In critical COVID-19 patients, the urinary biomarker [TIMP2]*[IGFBP7] were generally elevated, and were higher in severe AKI when sampled at 12 h after ICU admission, but not at other timepoints." (PMID 36673127, 2023). "The objective of this study was to assess the utility of [TIMP2]*[IGFBP7] biomarkers as predictors of severe AKI in a population of critically ill COVID-19 patients." (PMID 36673127, 2023). "A small study reported that patients with COVID-19-associated AKI and high levels of [TIMP-2] × [IGFBP7] were more likely to progress to renal replacement therapy than those with AKI but with low [TIMP-2] × [IGFBP7]." (PMID 35204776, 2022). "Significant differences were also detected in plasma levels of CXCL12, IL-17, TIMP-2 and IL-21R between mild and severe COVID-19 patients." (PMID 35087533, 2021). "On the other hand, our data revealed clear differences in TIMP-2 levels between severe and mild cases of COVID-19." (PMID 35087533, 2021). "IL-6 and IL-8 are key inflammatory cytokines elevated in severe COVID-19, suggesting that increased TIMP-2 and AAT may protect tissues from proteolytic damage." (PMID 40557167, 2025). "While urine alkalinization is feasible and can increase urine pH, we could not demonstrate differences in AKI rates or changes in urine [TIMP-2]x[IGFBP7] concentrations in critically ill COVID-19 patients." (PMID 40055234, 2025). "A clinical trial has been established to study whether TIMP-2 and IGFBP7 could identify patients with COVID-19 at risk of developing AKI early (NCT04393428), and the findings of this investigation will be made public in the future." (PMID 35930243, 2022). "Although it may serve as an early indicator of acute kidney stress, few studies have investigated the value and clinical application of [TIMP-2] • [IGFBP7] in COVID-19." (PMID 35930243, 2022). "The efficacy of urine TIMP-2 and IGFBP-7 to predict AKI in patients with COVID-19 has been examined." (PMID 39001241, 2024). "New cell-cycle arrest biomarkers [TIMP2]*[IGFBP7] have been proposed for early detection of AKI, but their role in critically ill COVID-19 patients is poorly understood." (PMID 36673127, 2023). "While research on the applications of TIMP2 and IGFBP7 is promising in some settings, it is scarce in the context of COVID-19, with few and contradictory results." (PMID 36673127, 2023). "More studies should be carried out to investigate the effect of [TIMP-2] • [IGFBP7] in predicting AKI and the progress of the disease and determine its clinical usage in the phenotyping of clinical AKI in patients with COVID-19." (PMID 35930243, 2022). "Patients who died from COVID-19 also presented with elevated Ang-2 and HGF levels, accompanied by low concentrations of TIMP-2." (PMID 35372407, 2022). "In view of the need to identify the early signs of kidney involvement, this study was aimed at exploring the role of the urinary biomarkers NGAL, TIMP-2, and IGFBP7 for the early detection of AKI in critically ill patients with COVID-19." (PMID 35204776, 2022). "The combination of [TIMP-2] × [IGFBP7] together with clinical information, were useful for the identification of subclinical AKI in critically ill COVID-19 patients." (PMID 35204776, 2022). "Increased levels of MMP-9, combined with our finding of TIMP-2 levels within normal limits throughout the observation period, suggest enhanced MMP-9 activity in these COVID-19 patients." (PMID 34853380, 2021).
COVID-19 (continued). "A previous set of cytokine quantification assays performed in a pilot screening of plasma soluble proteins with COVID-19 and CAP patients revealed differences in the plasma levels of IL-11, IL-17 and the tissue inhibitor of metalloproteinases 2 (TIMP-2)." (PMID 35087533, 2021). "Patients with COVID-19 AKI and high levels of tissue inhibitor of metalloproteinases-2 and insulin-like growth factor-binding protein-7 [TIMP-2] × [IGFBP-7] were more likely to progress to RRT than patients with AKI but with low [TIMP-2] × [IGFBP-7]64." (PMID 33060844, 2020). "Kidney injury biomarkers, such as functional biomarkers (CysC), damage biomarkers (KIM-1, L-FABP, IL-18, suPAR, and NGAL), and stress biomarkers (TIMP-2 and IGFBP7), appear to be efficient in detecting AKI as well as disease progression in patients with COVID-19." (PMID 35930243, 2022). "In contrast, renal TIMP-2 mRNA levels were low in bacterial sepsis (fold change 0.4, p = 0.017) but not COVID-19 patients compared to normal controls." (PMID 34112226, 2021). "Up-regulation of NGAL and [TIMP-2] × [IGFBP7] was already significant, indicating that these kidney stress biomarkers may be useful for the diagnosis of subclinical AKI in patients with COVID-19." (PMID 36499745, 2022).
pancreatic cancer (15 papers, 2013 to 2022). "In pancreatic cancer, tissue inhibitor of metalloproteinase 2 (TIMP2) was reported to be a direct functional target of miR-221/222." (PMID 36555512, 2022). "These miRNAs are overexpressed in pancreatic cancer cells, and, as a result, they promote cellular proliferation, invasion, and chemoresistance by targeting TIMP-2 or inducing the expression of the invasion-related genes matrix metalloproteinase-2 and -9." (PMID 32197468, 2020). "Studies of pancreatic cancer have shown that mir-106a has an oncogenic role through promoting cancer cell proliferation and invasion by targeting TIMP-2." (PMID 27039384, 2016). "Using a dual luciferase 3′ UTR reporter assay, we verified that miR-221/222 facilitates pancreatic cancer invasion by directly targeting TIMP-2, which is an inhibitor of MMPs." (PMID 25883224, 2015). "MMP1, MMP2 and MMP9, as well as their inhibitors, TIMP1 and TIMP2, were detected in pancreatic cancers, and their concentrations correlated with tumor grade, tumor size, invasive characteristics, and metastasis." (PMID 23744510, 2013). "Prior to surgery, the level of TIMP-2 in the pancreatic tumor patients was higher than in the control group." (PMID 23768069, 2013). "In pancreatic cancer, miR-106a expression is elevated and has an oncogenic role by promoting cell proliferation, epithelial-mesenchymal transition and invasion by targeting tissue inhibitors of metalloproteinase 2 (TIMP-2)." (PMID 28750689, 2017). "Thus, TIMP-2 is a pivotal target of miR-221/222-induced pancreatic cancer cell invasion." (PMID 25883224, 2015). "One investigation demonstrates no significant change in TIMP-1 and TIMP-2 in Panc-1, pancreatic cancer cells after gamma irradiation." (PMID 27659937, 2016). "The data show that highly expressed miR-221/222 could inhibit TIMP-2 and further upregulate the expression of MMP-2 and MMP-9, which would promote the invasion of pancreatic cancer cells." (PMID 25883224, 2015). "In a previous study, we found that miR-106a could promote pancreatic cancer cell invasion by upregulating MMP-2 and MMP-9, and we verified that TIMP-2 was the target of the miRNA." (PMID 25883224, 2015).
glioblastoma (14 papers, 2006 to 2025). The most malignant astrocytic tumor (WHO grade IV). "For TIMP2, the only significant changes in mRNA levels were present in the astrocytoma and glioblastoma group when the meningioma group was taken into account (p < 0.001 for both changes)." (PMID 38474106, 2024). "Overall, changes in fold regulation with statistical significance were recorded for MMP3 (p < 0.001), MMP10 (p < 0.001), and TIMP2 (p < 0.05) in glioblastoma." (PMID 38474106, 2024). "Phorbol myristate acetate-induced downregulation of TIMP-2 secretion was reversed by inhibition of p38 in glioblastoma cells." (PMID 18474097, 2008). "Moreover, using a human glioblastoma cell line model, it was demonstrated that up-regulation of TIMP-2 promotes MMP-2 activation and subsequent glioblastoma cell invasion." (PMID 26361584, 2015). "SIM2 regulates the expression of MMP-2 and TIMP-2, which drive its role in glioblastoma cells." (PMID 22174909, 2011). "ADAMTS1 negatively regulates tumor growth and metastasis, whereas TIMP2 takes part in degrading ECM (extracellular matrix) and regulating the invasion process, considered the root cause of the high recurrent incidence in glioblastoma." (PMID 21637621, 2010). "In addition, TRAIL potently suppresses the expression of tissue remodelling factors, such as MMP-2 and TIMP-2, as well as of those promoting glioblastoma invasiveness, such as SPARC." (PMID 16622457, 2006). "Particularly, the expression of the following genes was affected in A172 cells after 24 h of treatment with TRAIL: VEGF, the MMP-2, the gene encoding TIMP-2, a protein regulating the activity of MMP-2 and SPARC, a protein involved in glioblastoma invasiveness processes." (PMID 16622457, 2006). "Analysis of exosomes from glioblastoma cells showed that they are enriched with the proangiogenic factors VEGF, angiogenin, TGFβ, IL-8, IL-6, MMP2, MMP9, TIMP-1, TIMP-2, and CXCR4." (PMID 35740619, 2022). "It has also been shown that inhibition of GSK-3 down-regulates the expression of MMP-2 and MT1-MMP in glioblastoma cells and that MMP-2 activation is mediated by the interaction of its pro-form with another metalloprotease, MT1-MMP, and TIMP-2." (PMID 34235177, 2021). "A study carried out in the invasive glioblastoma cells showed that increase in local TIMP-2 concentrations has the effect of initially stimulating MMP-2 activation, whereupon exceeding amounts of TIMP-2 are inhibitory to MMP-2 activation." (PMID 24591757, 2014). "Notably, patients with glioblastomas exhibited almost consistently elevated protein levels compared to the other groups, except for MMP10 and TIMP2." (PMID 38474106, 2024). "Moreover, the expression of MMP-2, its inhibitor TIMP-2 and the tumour invasiveness-related protein SPARC were effectively inhibited by TRAIL in glioblastoma cell lines." (PMID 16622457, 2006). "Overall, the bulk of data demonstrate that an altered ratio between TIMP-2 and MMP-2 may be related to glioblastoma invasiveness." (PMID 16622457, 2006).
non-small cell lung carcinoma (14 papers, 2015 to 2025). A group of at least three distinct histological types of lung cancer, including non-small cell squamous cell carcinoma, adenocarcinoma, and large cell carcinoma. "TIMP2 expression is negatively regulated by the microRNA, miR-410, and is associated with non-small-cell lung cancer progression." (PMID 36624735, 2022). "Consistent with that study, silencing miR939 produced an overexpression of endogenous TIMP-2 with consequent significant loss of proliferation of non-small cell lung cancer cell line (NSCLC)." (PMID 33023532, 2020). "For example, miR-130b promotes cancer metastasis by acting as an oncomiR and downregulating TIMP-2 and the invasive activity of non-small cell lung cancer cells." (PMID 40420632, 2025). "Another study of non-small cell lung cancer has proved that TIMP2 was a predicted downstream target of miR-761." (PMID 29220395, 2017). "Moreover, miR-15b-5p was shown to promote cell viability, migration, and invasion in non-small cell lung cancer by targeting metastasis suppressor TIMP2." (PMID 29930741, 2018). "In non-small cell lung cancer(NSCLC), TIMP-2, as a protective factor, is up-regulated and related to the prognosis." (PMID 37823051, 2023). "In contrast, miR-221 acted as an oncogene in non-small-cell lung carcinoma, and upregulation of miR-221 promoted the malignant biological behavior of SPCA1 and H1299 cell lines by directly targeting TIMP2 at both the mRNA and protein levels." (PMID 29467441, 2018). "Recently, TIMP-2 overexpression was detected in the lungs of mice with Lewis lung carcinoma and was positively correlated with tumor progression in non-small cell lung carcinoma (NSCLC)." (PMID 26556867, 2015). "Additionally, TIMP2 influences MMP14 activity, and overexpression of MMP14 is observed in epithelial and stromal cells in non-small-cell lung cancer patients and neurodegeneration and age-related changes." (PMID 36624735, 2022).